RAC1 (Rac family small GTPase 1)
Diseases named in the same sentence as RAC1 in open-access papers (continued):
Sharing a sentence is not in itself a finding about the gene and the disease.
colorectal cancer (continued). "Summary of the roles of RAC1 and RAC1B in normal intestinal epithelium and colorectal cancer." (PMID 39001533, 2024). "Another investigation discovered that CSDE1 could regulate the expression of c-Myc, Rac-1, PTEN, and vimentin in colorectal cancer." (PMID 35923244, 2022). "Similarly, Rac1 is overexpressed in colorectal cancer (CRC), where Rac1 is shown to co-immunoprecipitate with STAT3 in HCT116 CRC cells." (PMID 32915198, 2020). "Previous studies have shown that miR-320a is downregulated in colorectal cancer and targets the small GTPase Rac1, leading to a reduction in noncanonical WNT signaling and EMT, thereby inhibiting tumor metastasis and invasion." (PMID 31515469, 2019). "Understandably, RAC1 plays an important role in EMT by virtue of its property to regulate cell polarity, migration, invasion, and stemness in different cancers including gastric adenocarcinoma, squamous lung cancer, and colorectal cancers." (PMID 31027363, 2019). "In mouse models, genetic deletion of Rac1 decreased hyperproliferation and suppressed the expansion of intestinal stem cells in APC-null crypts, implying that Rac1 activation contributes to Wnt-driven colorectal cancer growth." (PMID 26403202, 2015). "We conclude that, in the tested colorectal cancer cell lines, the level of active Cdc42 and Rac1, but not of RhoA, is inversely correlated with the invasiveness of such cells (respective p values: 0.0008, 0.0003 and 0.134)." (PMID 23144867, 2012). "We show that the ability to invade of these colorectal cancer cell lines is correlated with a marked decrease in Cdc42 and Rac1 activity and an increase in ROCK, but not RhoA, activity." (PMID 23144867, 2012). "However, we now found that deletion of Pals1 in other colorectal cancer cell lines did not result in enhanced Arf6/Rac1-dependent cell migration." (PMID 36494580, 2023). "Examples discussed in this review include Cdc42, Rac1, RhoA, RhoC and RhoH activation of oncogenic STAT3, and in some cases STAT5, in a range of cancers including but not limited to: breast, bladder, gastric, cervical, myeloid, pancreatic, hepatocellular, head and neck, and colorectal cancer." (PMID 32915198, 2020). "Thus further understanding of the mechanism by which Rac1 modulates the interaction between LEF-1 and β-catenin may provide an alternative therapeutic avenue to reduce β-catenin–LEF-1 signaling in colorectal cancer." (PMID 26403202, 2015). "Notably, deletion of Pals1 in three other colorectal cancer cell lines (Caco-2, DLD1 and RKO) alone does not increase cell migration or Arf6/Rac1 activity, due to the expression of the Arf6-specific GAP SMAP1." (PMID 36494580, 2023).
pancreatic cancer (70 papers, 2009 to 2025). "For instance, elevated RAC1 expression is associated with aggressiveness and poor prognosis in colorectal, breast, lung, thyroid, and pancreatic cancers." (PMID 40736275, 2025). "Above, we have shown that ALK2 represses RAC1 and RAC1b, which have both been implicated in driving invasion, metastasis, and pancreatic cancer progression, providing a mechanistic basis for ALK2′s antimigratory activity." (PMID 36289908, 2022). "The well-known function of Vav1 as the tyrosine phosphorylation–dependent GEF activity for Rac1 was previously shown to be linked to an increase in tumorigenic properties of pancreatic cancer." (PMID 32277014, 2020). "The effect of the alterations on radiosensitivity caused by RAC1 inhibition is markedly increased in radiosensitivity of pancreatic cancer cells, as demonstrated by caspase-3 activation." (PMID 32411607, 2020). "Rac1 has previously been implicated in pancreatic cancer progression and is thought to regulate actin localisation and dynamics during dysplastic changes in precancerous regions of pancreas as well." (PMID 31413787, 2019). "In pancreatic cancers, Rac1 hyper-activation has also been implicated in the development and maintenance of Ras-mediated tumorigenesis." (PMID 28410221, 2017). "The net effect of these alterations caused by Rac1 inhibition is a marked increase in radiosensitivity of pancreatic cancer cells, as demonstrated by caspase 3 activation, production of floating cells and the results of clonogenic survival assays." (PMID 25344910, 2014). "Aberrant expression of Vav1, a Vav family member of GEFs, is frequently observed in pancreatic cancer and associated with active Rac1 and worse prognosis." (PMID 23408967, 2013). "In summary our data suggest that in pancreatic carcinoma cells activated Rac1 interacts with IQGAP1, which is associated with a disassembly of E-cadherin-mediated adherens junctions and with increased cell migration and invasion of pancreatic carcinoma cells." (PMID 19737400, 2009). "Thus, in mice, Rac1 is required for early metaplastic changes and neoplasia-associated actin rearrangements in the development of pancreatic cancer." (PMID 32277014, 2020). "Consequently, Rac1 activity has been implicated in a number of cancers, including breast, colon, prostate, and pancreatic cancer." (PMID 28410221, 2017). "Rac1 and two of its GEFs, Tiam1 and Vav1, have been reported to be overexpressed in more than 70% of pancreatic cancers, and Vav1 overexpression has also been associated with poor prognosis in pancreatic cancer patients." (PMID 25344910, 2014). "The YAP and Rac1 proteins were separately reported to be up-regulated in pancreatic cancer (PC) specimens." (PMID 39518045, 2024). "Consistently, DEPDC1B was able to promote migration and invasion of pancreatic cancer cell through Rac1/PAK1-LIMK1-Cofilin1 pathway." (PMID 35706026, 2022). "This seems reasonable because previous accounts reported the overexpression of Rac1 in human patient samples of breast, gastric, testicular, oral squamous cell, lung, and pancreatic cancers." (PMID 33747247, 2021). "RAC1 activation has been related to most cancers, such as cutaneous melanoma, breast, lung, and pancreatic cancer." (PMID 34827551, 2021). "The knockdown of IQGAP1 reduced cell proliferation and migration in pancreatic cancer cells in a CDC42/RAC1-dependent manner." (PMID 34439095, 2021). "Inhibition of Rac1 with specific inhibitors of Rac1 not only eliminates the activation of G2 checkpoints induced by radiotherapy (IR) but also improves the sensitivity of pancreatic cancer cells to radiotherapy by inducing apoptosis." (PMID 34079763, 2021). "Data from the pancreatic cancer model have shown that the small GTPase RAC1 and its alternatively spliced isoform, RAC1B, antagonistically control epithelial–mesenchymal transition and cell motility induced by transforming growth factor β." (PMID 33567745, 2021).
pancreatic cancer (continued). "Recently, it has been identified that the RAC1 signaling pathway is an important regulator of the response of breast and pancreatic cancer cells to IR." (PMID 32411607, 2020). "Vav1 also regulated pancreatic cancer cell migration via Rac1, and its expression was correlated with pancreatic cancer cell lines but not in the normal human pancreas." (PMID 32322580, 2020). "Although RAC1 has been found to promote TGFβ-driven tumor progression, recent observations in pancreatic carcinoma cells surprisingly revealed that RAC1B confers anti-oncogenic properties, i.e., through inhibiting TGFβ-induced EMT." (PMID 33266416, 2020). "Since Rac1 is a key mediator of EMT in pancreatic cancer, and it has been shown that the Rac1-related isoform, Rac1b, acts as an endogenous inhibitor of Rac1 in TGFβ signalling, we analyzed Rac1b and Rac1 + Rac1b expression in PRP treated cells by RTqPCR." (PMID 31388092, 2019). "More recently, in pancreatic tumor cells, dynamin 2 was found to promote lamellipodia formation and pancreatic tumor cell migration by its direct binding with Vav1 to promote Rac1 activation and migration." (PMID 28402939, 2017). "In mice implanted with pancreatic tumors, intratumoral injections of an adenovirus expressing the RAC1-T17N mutant have also led to significant tumor growth inhibition." (PMID 28499439, 2017). "In PDAC progression the RAC1 GEF VAV1 has been shown to possess a role by acting synergistically with the EGFR to stimulate pancreatic tumor cell proliferation." (PMID 28499439, 2017). "To choose the best cell line for the study, we first assessed the expression of Cdc42, RhoA and Rac1 in a panel of pancreatic cancer cell lines." (PMID 28410221, 2017). "Aberrant activation of Rho GTPase Rac1 has been observed in various tumor types, including pancreatic cancer." (PMID 28410221, 2017). "Many GEFs such as Vav1 and Tiam1 that are overexpressed in pancreatic cancer are known to promote Rac1 activation." (PMID 28410221, 2017). "In a mouse model of pancreatic cancer, Rac1 knockdown was shown to reduce tumor formation and prolong survival." (PMID 28410221, 2017). "We have previously observed both elevated Rac1 level and elevated Rac1 activity in pancreatic cancer cells compared to normal pancreatic ductal cells, thus making hyper-activated Rac1 a promising therapeutic target for pancreatic cancers." (PMID 28410221, 2017). "The two inhibitors, #1 and #6, are selective for Rac1 and reduce cell growth and migration in pancreatic cancer cell lines." (PMID 28410221, 2017). "In breast and pancreatic cancer cells, RAC1 inhibition reduces survival and blocks activation of a G2/M cell cycle checkpoint, respectively, and sensitizes pancreatic cancer cells to γ-irradiation." (PMID 28499439, 2017). "In already established tumors, blocking RAC1 signaling in pancreatic cancer cells in vitro has led to reductions in cell proliferation, viability, and migration." (PMID 28499439, 2017). "BART inhibits pancreatic cancer cell invasion by RAC1 inactivation through direct binding to active RAC1 and microRNA-124 (miR-124) suppresses RAC1 expression." (PMID 28499439, 2017). "In turn, carbon-ion irradiation suppresses migration and invasiveness of human pancreatic carcinoma cells MIAPaCa-2 via RAC1 and RHOA degradation." (PMID 28499439, 2017). "This article focusses on the role of TGF-β and its signaling crosstalk with the RHO family GTPases RAC1 and RAC1b in the progression of breast and pancreatic carcinoma." (PMID 28499439, 2017). "VAV guanine nucleotide exchange factor 1 (VAV1) is reported to be overexpressed in clinical pancreatic carcinoma cells, leading to activation of Rac1 signaling, resulting in decreased survival in pancreatic cancer patients." (PMID 27145964, 2016). "Plexin A1 activation via SEMA3 treatment in different pancreas cancer cell lines has been previously shown to activate Rac1, GSK3β and p44/p42 MAPK signaling." (PMID 26962861, 2016).
pancreatic cancer (continued). "We also found that the depletion of ARHGEF15 by RNA interference in pancreatic cancer cell lines downregulated the activities of molecules of the Rho signaling pathway, including RhoA, Cdc42 and Rac1." (PMID 27145964, 2016). "ATM treatment inhibits Rac1 activity in pancreatic cancer cells consistent with inhibition of PKCι signaling." (PMID 25915428, 2015). "PKCι promotes the transformed phenotype of pancreatic cancer, at least in part, via activation of Rac1-MEK/ERK signaling, whereas a major mechanism by which PKCζ regulates pancreatic cancer cell transformed growth is via promotion of STAT3 activation." (PMID 25915428, 2015). "In this report, we provide evidence that the Rac1 pathway also plays an essential role in the response of pancreatic cancer cells to IR." (PMID 25344910, 2014). "We also tested the effect of Rac1 inhibition on the viability of irradiated HPNE normal cells, which express a much lower level of Rac1 protein relative to CD18/HPAF pancreatic cancer cells." (PMID 25344910, 2014). "In the present study, we have investigated the role of Rac1 in the response of human pancreatic cancer cells to IR." (PMID 25344910, 2014). "The pancreatic cancer cells expressed much higher levels of Rac1 than HPNE primary human pancreatic ductal cells." (PMID 25344910, 2014). "Here, we show that Rac1 also plays a critical role in the response of pancreatic cancer cells to IR." (PMID 25344910, 2014). "The Rac1 signaling pathway is required for transformation mediated by the Ras oncogene and, in the mouse K-RasG12D knock-in model of pancreatic cancer, Rac1 is required for the development of tumors." (PMID 25344910, 2014). "Rac1 is constitutively activated in the great majority of pancreatic cancers and contributes critically to the development and maintenance of pancreatic cancer." (PMID 25344910, 2014). "Our data show that the inhibition of Rac1 abrogates the IR-induced G2 checkpoint activation in the pancreatic cancer cells but only has subtle, if any, effect on the IR-induced G1 and G2 checkpoint responses of the normal HPNE cells." (PMID 25344910, 2014). "To address this issue, we have compared the response of pancreatic cancer cells to IR and Rac1 inhibition with that of normal pancreatic ductal cells." (PMID 25344910, 2014). "To investigate the possible mechanisms involved in the increase in radiation sensitivity in pancreatic cancer cells by Rac1 inhibition, we assessed the treated cells for markers of apoptosis induction." (PMID 25344910, 2014). "Overexpression/hyperactivation of Rac1 in pancreatic cancer cells has been reported and Rac1 plays an important role in cell survival and transformation." (PMID 25344910, 2014). "Results in this report demonstrate that the inhibition of Rac1 sensitizes human pancreatic cancer cells to IR by a mechanism that involves G2 checkpoint abrogation and apoptosis induction." (PMID 25344910, 2014). "Overexpression/hyperactivation of Rac1 has been detected in the great majority of pancreatic cancers." (PMID 25344910, 2014). "First, there is a marked difference in Rac1 activity between the normal pancreatic ductal cells and pancreatic cancer cells." (PMID 25344910, 2014). "Using the Rac1 specific inhibitor NSC23766, we examined the effect of Rac1 on IR-induced G2/M arrest in pancreatic cancer cells." (PMID 25344910, 2014). "Most significantly, survival of normal pancreatic ductal cells following IR is only marginally affected by the inhibition of Rac1, in stark contrast with the radiosensitization observed in the pancreatic cancer cell lines." (PMID 25344910, 2014). "We found RhoA is the most important small GTPase for CTHRC1-mediated HCC invasion and they found Rac1 accounts for the invasiveness in pancreatic cancer." (PMID 23922981, 2013). "Treatment with 10 μM AR-A014418 reduced the levels of p-FAKY397 and p-FAKY861, suggesting a pivotal role for the GSK3β/FAK/Rac1 pathway in promoting pancreatic cancer cell invasion." (PMID 23408967, 2013).
pancreatic cancer (continued). "A previous study indicated that Rac1 destabilizes E-cadherin-mediated cell adhesion in pancreatic cancer by interacting with IQGAP1, thereby promoting cancer cell migration." (PMID 23408967, 2013). "The GTP-Rac1 forms, which bound to the Rac binding domain of Pak1 coupled to agarose beads, were quantified and compared to total Rac1 in pancreatic cancer cell lysates by Western blot analysis." (PMID 24281169, 2010). "The aim of this study was to characterise the function of Rac1 in epithelial cell differentiation and migration, especially during carcinogenesis of pancreatic cancer cells." (PMID 19737400, 2009). "Our results emphasise a regulatory role of Rac1 in promoting pancreatic tumour cell migration and metastasis." (PMID 19737400, 2009). "An enhanced expression of Rac1 has been documented for pancreatic cancer tissue and pancreatic carcinoma cell lines and active Rac1 is necessary for cell migration and invasion in pancreatic tumours after HGF or LPA-stimulation." (PMID 19737400, 2009). "Here, we show that the activity of the monomeric GTPase Rac1 contributes to inhibition of E-cadherin-mediated cell-cell adhesion in pancreatic carcinoma cells." (PMID 19737400, 2009). "In the present study we have analysed the influence of the Rho-GTPase Rac1 on E-cadherin-mediated cell-cell adhesion in the pancreatic carcinoma cell line PANC-1." (PMID 19737400, 2009). "Stable expression of constitutively active Rac1(V12) reduced the amount of E-cadherin on protein level in PANC-1 pancreatic carcinoma cells, whereas expression of dominant negative Rac1(N17) resulted in an increased amount of E-cadherin." (PMID 19737400, 2009). "It has been reported that TIPE3 may promote tumor progression via increasing RAC1 expression in pancreatic cancer." (PMID 40904408, 2025). "In contrast, inhibition of RAC1 GTPase sensitizes to γ-irradiation in pancreatic cancer cells." (PMID 32411607, 2020). "Furthermore, metastasis in a pancreatic cancer mouse model was shown to be inhibited with azathioprine through inhibition of the activity of Vav1 as a GEF towards Rac1." (PMID 32277014, 2020). "Rac1 expression is increased in mouse and human pancreatic tumors, particularly in the stroma, and is generally a consequence of enhanced upstream inputs from receptor tyrosine kinases and phosphatidylinositol 3-kinases (PI3Ks) or of reduced Rac inactivation by GTPase-activating proteins (GAPs)." (PMID 32277014, 2020). "Moreover, DEPDC1B was found to be able to promote migration and invasion of pancreatic cancer through Rac1/PAK1-LIMK1-Cofilin1 signal pathway." (PMID 33203836, 2020). "The similar role played by RAC1 was observed in pancreatic cancer cells." (PMID 32411607, 2020). "Additionally, we show that both compounds preferentially down-regulate Rac1 activity compared to Cdc42 and RhoA in pancreatic cancer cells." (PMID 28410221, 2017). "In pancreatic cancers, more than 70% of tumors overexpressed the Rac1 GEFs Tiam1 and Vav1." (PMID 28410221, 2017). "In more than 70% of pancreatic cancer, overexpression of Rac1 has been observed." (PMID 28410221, 2017). "Different cell factors are demonstrated to be involved in the regulation of dynamin 2 function, for example, dynamin 2 is regulated by proto-oncogenic expression of K-RAS in human colon cancer cells and promotes pancreatic cancer cell migration through activation of Rac1." (PMID 28402939, 2017). "Rac1, another Rho family GTPase, is also involved in various cancers, and down-regulation of Rac1 expression inhibits proliferation, viability, and migration in pancreatic cancer cells." (PMID 27613829, 2016). "Recent publications reported that Rac1 could inhibit E-cadherin mediated adherens junctions in pancreatic carcinoma cells." (PMID 27231134, 2016).